SERPINB2 (serpin family B member 2)
Diseases named in the same sentence as SERPINB2 in open-access papers (continued):
Sharing a sentence is not in itself a finding about the gene and the disease.
cancer (continued). "The presence of SerpinB2 on the surface of MPs provides a physiological mechanism whereby cancer cell SerpinB2 can reach the extracellular milieu and access urokinase plasminogen activator (uPA)." (PMID 24644264, 2014). "SerpinB2 expression by cancer cells did, however, significantly reduce the number of metastases in a B16 metastasis model." (PMID 24644264, 2014). "SerpinB2 is expressed by a range of cells including cancer cells, monocyte/macrophages, fibroblasts, endothelial cells, and dendritic cells and is often upregulated during inflammatory conditions." (PMID 24644264, 2014). "In agreement with our findings, previous research has demonstrated a notable upregulation of SERPINB2 expression in human umbilical cord blood stem cells 53, endometrial stem cells 54, and various types of cancer stem cells 55 upon exposure to multiple toxic substances." (PMID 39744426, 2025). "Consistent with our results, previous studies have shown that exposure to various toxic substances leads to a significant increase in SERPINB2 expression in various stem cell types, including cancer stem cells 49, human endometrial stem cells 50, and umbilical cord blood stem cells." (PMID 39664582, 2024). "SerpinB2 is a protumorigenic or antitumorigenic gene depending on the cancer type." (PMID 35768767, 2022). "We previously reported that SERPINB2 (a ~ 60 kDa serine protease inhibitor) might serve as a reliable marker of toxic response to various hazardous compounds in multiple types of cancer stem cells and cord blood stem cells." (PMID 35932085, 2022). "Co-culture of melanoma cells with endothelial cells composing the abluminal surface of blood vessels, was demonstrated to induce the expression of genes linked to cancer cell migration (CCL2, ICAM1), cancer progression (TRAF1, SERPINB2) or stem cell properties (PDGFB; CFDP1)." (PMID 34604096, 2021). "Notably, the growth and stem cell-like properties of CSCs were successfully suppressed by SERPINB2 knockdown in multiple cancer types." (PMID 30965654, 2019). "How SerpinB2 might reach the extracellular milieu has been controversial; however, SerpinB2 externalization via microparticle formation has recently been illustrated for macrophages, cancer cells and syncytiotrophoblasts." (PMID 31455834, 2019). "Recently, SerpinB2 in BCCs was shown to promote cancer cell survival and metastatic outgrowth by converting astrocytic FasL into a paracrine death signal for cancer cells, and by inactivating L1 cell adhesion molecule (L1CAM) to spread metastatic cells along brain capillaries." (PMID 28427146, 2017). "SERPINB2 was decreased while UPA was increased in cancer cells compared to MRC5 cells." (PMID 27558531, 2016). "We also considered the analysis of recurrence of cancer, and we found that the level of gene expression in the normal tissue was associated with recurrence for many genes: FOXC2, CDC20, OCLN and SERPINB2 (p = 0.0067, p = 0.0067, p = 0.048 and p = 0.0352 respectively)." (PMID 25575813, 2015). "However, we were unable, in several settings, to observe any significant effects of SerpinB2 expression on cell growth or cell cycle in vitro, or cancer growth in vivo." (PMID 24644264, 2014). "A number of mechanisms whereby SerpinB2 expression by the cancer cells might influence tumorigenesis have been proposed, including inhibition of apoptosis 1,9, growth 10,11, and/or uPA receptor signaling." (PMID 24644264, 2014). "Perhaps the best described mechanism whereby SerpinB2 expression by cancer cells might improve prognosis is via reduction of uPA-dependent migration/invasion and metastases 13–15." (PMID 24644264, 2014). "Thus, the role of SerpinB2 in cancer development and aggressive progression may depend on the cancer type." (PMID 35768767, 2022).
cancer (continued). "Importantly, for the first time we identified, a labile tumorigenic response gene—SERPINB2—and showed that tumorigenic compound exposure more profoundly affected its expression in CSCs than in non-stem cancer cells, although both cells exhibit basal expression of SERPINB2 in multiple cancer types." (PMID 30965654, 2019). "The genes encoding PAI-1 (SERPINE1) and PAI-2 (SERPINB2) are regulated by different types of growth factors [transforming growth factor beta (TGF-β) and insulin-like growth factor 1], hormones (insulin), and cytokines (tumor necrosis factor α) that typically shows aberrant expression in cancer." (PMID 29484286, 2018). "The down-regulated genes included palmitoleoyl-protein carboxylesterase (NOTUM), which is known to affect the Wnt signaling pathway, and serpin family B member 2 (SERPINB2), a gene related to autophagy and senescence in cancer." (PMID 38541076, 2024). "Mechanistically, ID1 interacts with STAT1 to induce its cytoplasmic distribution and inhibits STAT1-mediated SerpinB2 and CCL4 transcription, two secretory factors responsible for cancer stemness inhibition and CD8+ T cell recruitment." (PMID 37996458, 2023). "Cells positive for SERPINB2 were also largely positive for CD44, CD133 or ALDH in each cancer tissue sample." (PMID 30965654, 2019). "Specifically, SERPINB2 may counteract the distinctive functions attributed to SERPINE1, particularly in the context of cancer prognosis." (PMID 39376567, 2024). "On the basis of previous data showing that SERPINB2 can impair cancer cell migration, invasion, and metastasis, we investigated whether E4 was able to regulate the motile phenotype of TNBC cells through SERPINB2 induction." (PMID 38741146, 2024). "The analysis of the cancer coagulome found expression of genes encoding six pro‐coagulant and fibrinolytic factors (F3, PLAU, PLAT, PLAUR, SERPINB2, and SERPINE1) in The Cancer Genome Atlas, and correlated with VTE incidence in 32 cancer types in a previously reported Dutch study." (PMID 37147936, 2023). "The identified up-regulated genes with H3K27Ac engagement included the inflammatory response genes IL1α, IL1β, and SERPINB2; the HBEGF gene that mediates cell migration and invasion; PLAU, which is regulated by AP-1 and drives cancer metastasis; and LAMC2, which is involved in the EMT process." (PMID 37511268, 2023). "Our data revealed that the expression of an identified potential tumorigenic marker, SERPINB2, in multiple CSC types was significantly higher than that in non-stem cancer cells, although both non-stem cancer cells and CSCs exhibit basal expression of SERPINB2." (PMID 30965654, 2019). "The exact mechanisms of SerpinB2 function in different cancer types is to date not fully understood." (PMID 29207598, 2017). "Compared to SERPINB2 expression, UPA levels were relatively lower in MRC5 cells and higher in H292-Gef cells; therefore, the ratio between two genes was different in normal and cancer cells." (PMID 27558531, 2016). "SerpinB2 is involved in diverse cellular functions including cell survival, cell differentiation, inflammation, immunity, cell adhesion, migration, and extracellular matrix (ECM) remodeling in diseases including cancer by interacting with intracellular and extracellular proteins." (PMID 35768767, 2022).
infection (23 papers, 2013 to 2025). The state of being infected such as from the introduction of a foreign agent such as serum, vaccine, antigenic substance or organism. "We thus quantitated SerpinB2 mRNA expression levels using qRT-PCR in serial PBMC samples from pigtail macaques following infection with either SIVmac251 or the pathogenic SHIVmn229." (PMID 23460840, 2013). "SerpinB2 is one of the most strongly induced proteins in macrophages during infection and inflammation and is emerging as a novel regulator in the macrophage immune response." (PMID 38956496, 2024). "Its expression is acutely upregulated in pregnancy and inflammation an infection state, and was also demonstrated during the in vitro culture of porcine granulosa cells (pGCs), while a decreased expression SERPINB2 was noted during the culture of porcine OECs." (PMID 39000215, 2024). "The stimulation of samples from early time points after the infection led to the increase in the expression of other inflammatory genes like Serpinb2 and Chil1 (Chitinase-3-like protein 1), and these values started to decrease in the subsequent days." (PMID 35795182, 2022). "SERPINB2 is highly expressed during inflammation, infection, and tissue damage, indicating its immune features." (PMID 34095322, 2021). "SerpinB2 is also one of the most up-regulated proteins in monocyte/macrophages following infection or stimulation with inflammatory mediators, representing up to 0.25% of total intracellular protein under these conditions." (PMID 26083412, 2015). "The increase in the protease inhibitor SerpinB2 is interesting but should be interpreted with caution as a role has yet to be identified in host infection responses." (PMID 24357630, 2014). "The viral load in these monkeys peaked at week 2 post infection, one week prior to the peak SerpinB2 induction (SIV)." (PMID 23460840, 2013). "Herein we show that SerpinB2 is induced in peripheral blood mononuclear cells following infection of pigtail macaques with CCR5-utilizing (macrophage-tropic) SIVmac239, but not the rapidly pathogenic CXCR4-utilizing (T cell-tropic) SHIVmn229." (PMID 23460840, 2013). "SerpinB2, also known as plasminogen activator inhibitor type 2, is a major product of activated monocytes/macrophages and is often strongly induced during infection and inflammation; however, its physiological function remains somewhat elusive." (PMID 23460840, 2013). "The SerpinB2 mRNA levels in EcoHIV infected mice decreased significantly by ≈50% on days 21 and 41 post infection in both PECs (p = 0.032 and 0.008, respectively) and spleen (p = 0.029 and 0.016, respectively)." (PMID 23460840, 2013). "In contrast, infection with the CXCR4-tropic SHIVmn229 resulted in a reduction in SerpinB2 mRNA levels in PBMCs; levels had fallen significantly by week 3 and remained depressed until week 11 (SHIV, p = 0.008 and 0.04, respectively)." (PMID 23460840, 2013). "SerpinB2 upregulation in monocytes/macrophages following infection or stimulation with inflammatory mediators is involved in a cellular response to delay cell death, possibly allowing cells to complete vital functions such as lymphocyte activation and antigen presentation." (PMID 35768767, 2022). "Serpin peptidase inhibitor, clade B (ovalbumin), member 2 (SERPINB2) is often expressed in lymphoid organs such as the spleen and in inflammatory responses or subjected to induced expression under various conditions of infection and pro-inflammatory stimuli." (PMID 36325528, 2022). "SERPINB2 is highly expressed in pregnancy, infection and inflammation." (PMID 28883483, 2017). "For instance, late stage aortic plaque rupture is influenced by the blood clotting/coagulation cascade, three components of which, Fga, Fgb and Serpinb2, were strongly down-regulated during infection with P. gingivalis, indicating a decreased tendency for blood clotting." (PMID 24836175, 2014).
infection (continued). "Based on the our assumption that AAV can provoke oxidative stress in MSC, we analyzed the mRNA expression of two antioxidant enzymes: Peroxiredoxin 5 (PRDX5) and Mn superoxide dismutase (SOD2), SERPINB2 and HSP90 in human MSC after 7 days post infection." (PMID 34494647, 2021). "These two features of EcoHIV infections differ from human HIV infections, where Th1 cytokines usually dominate during the acute phase, and gp120 and infection can induce SerpinB2 expression in monocytes/macrophages in vitro." (PMID 23460840, 2013). "Importantly, the EcoHIV infection model both in vivo and in vitro suggests that SerpinB2 expression by the infected cell does not affect lentiviral replication directly, as was suggested by previous studies." (PMID 23460840, 2013). "An exception to this trend was regulation of SERPINB2 and TNFAIP6, which showed similar upregulation regardless of infection mode." (PMID 34925266, 2021). "Of these genes expressed by SMs in response to infection with UT127, 17 genes were common to AMs response to infection with Mtb (although with a lower fold-change compared to AM), whereas only one gene (SERPINB2) was expressed exclusively by SMs (data not shown)." (PMID 32373118, 2020).
bacterial infection (4 papers, 2013 to 2025). "Furthermore, C/EBP-β-null mice are susceptible to bacterial infection and SerpinB2 has been demonstrated to protect from bacterial and viral-induced cell death." (PMID 23472114, 2013). "Second, the Basal.MUC16 cluster showed a significant increase (adjusted p < 0.05) in genes associated with bacterial infection (PDZD3, SFTPA2, PIK3C2B), cytokine signaling (TRIM31, SERPINB2), and apoptosis (BCL2L15, VIL1)." (PMID 39935174, 2025). "The expression of the PAI-2 SERPINB2 gene is induced by inflammatory mediators such as TNF-α and lipopolysaccharides or by viral and bacterial infections." (PMID 35008762, 2021).
adenocarcinoma (2 papers, 2015 to 2017). A common cancer characterized by the presence of malignant glandular cells. "Among stage I adenocarcinomas, low SerpinB2 expression was still associated with reduced LCSS (p = 0.031)." (PMID 29207598, 2017). "In the final model for stage I adenocarcinomas, SerpinB2 retained independent prognostic value for LCSS (HR 2.6 (95 % CI 1.03-6.58), p = 0.043)." (PMID 29207598, 2017). "In multivariate survival analysis of adenocarcinomas, low SerpinB2 demonstrated independent prognostic value (HR 1.8, p = 0.008)." (PMID 29207598, 2017). "This was also found in stage I adenocarcinomas, and SerpinB2 levels could potentially help stratify patients for closer follow-up and adjuvant therapy." (PMID 29207598, 2017). "Whereas low SerpinB2 expression was prognostic for survival in adenocarcinomas, there were no survival differences in SCC or other NSCLC when all stages were included." (PMID 29207598, 2017).
head and neck tumor (1 paper, 2016). "SERPINE1 (PAI-1) increases cisplatin resistance of head and neck tumor cells, while SERPINB2 (PAI-2) increases sensitivity." (PMID 27385000, 2016).
infectious disease (1 paper, 2019). A disorder directly resulting from the presence and activity of a microbial, viral, or parasitic agent in humans. "Additionally, some of these target genes, including SOD2, TNFAIP3, ARG1, SERPINB2, VLDLR, HSPA5, and LCN2, are associated with infectious diseases, suggesting that lncRNAs respond to PCV2 infection by regulating these genes." (PMID 30863688, 2019).
kidney disease (1 paper, 2025). "Their family member SERPINB2 also associated with renal injury and kidney disease through regulation of macrophage phagocytosis and migration." (PMID 40034749, 2025).
SERPINB2 also shares sentences with these, for which no sentence is quoted: preeclampsia (11 papers); atherosclerosis (8); endothelial dysfunction (7); Insulin resistance (6); metabolic syndrome (6); placental insufficiency (6); myocardial infarction (5); cardiovascular disease (4); Hyperinsulinemia (4); ischemic stroke (4); keloid (4); lymph node metastasis (4); non-small cell lung carcinoma (4); Brain infarct (3); colon cancer (3); endometriosis (3); gastric cancer (3); heart failure (3); thrombophilia (3); Antiphospholipid antibody syndrome (2); atopic asthma (2); brain injury (2); coagulation disorder (2); endometrial cancer (2); esophageal squamous cell carcinoma (2); glioblastoma (2); glioma (2); hematological diseases (2); hepatocellular carcinoma (2); hyperandrogenism (2).
A further 97 diseases each share a sentence with SERPINB2 in 2 papers or fewer.